GPR173 (G protein-coupled receptor 173)
Description:
Is a receptor for the SMIM20 derived peptides Phoenixin-14 and Phoenixin-20 (By similarity). It mediates the Phoenixin-14 and Phoenixin-20 augmentation of gonadotropin-releasing hormone (GNRH) signaling in the hypothalamus and pituitary gland (By similarity). In the ovary, it mediates the effects of Phoenixin-14 and Phoenixin-20 induced granulosa cell proliferation during follicular growth.
Synonyms: SREB3
Tractability: Small molecule: it belongs to a druggable protein family. Antibody: UniProt places it where antibodies can reach, with high confidence; UniProt predicts a signal peptide or a membrane-spanning region; its Gene Ontology location is reachable by antibodies, with medium confidence; the Human Protein Atlas places it where antibodies can reach. PROTAC: ubiquitination databases record sites on it.
Target class: Family A G protein-coupled receptor; Membrane receptor
Gene: Protein-coding gene on chromosome X (53,048,789 to 53,080,615, forward strand). Ensembl gene ENSG00000184194.
Subcellular location: Cell membrane
Subcellular location (Human Protein Atlas): Cytosol; Plasma membrane
Gene Ontology:
Molecular function: protein binding; G protein-coupled receptor activity; gonadotropin-releasing hormone receptor activity
Biological process: signal transduction; cellular response to gonadotropin-releasing hormone; G protein-coupled receptor signaling pathway
Cellular component: plasma membrane; membrane
Homologues: Orthologues: chimpanzee GPR173 (100% identical), macaque GPR173 (100% identical), pig GPR173 (100% identical), rabbit GPR173 (100% identical), dog GPR173 (99% identical), mouse Gpr173 (99% identical), rat AABR07037489.1 (99% identical), guinea pig GPR173 (98% identical), zebrafish gpr173 (81% identical), tropical clawed frog gpr173 (80% identical). Paralogues in human: GPR85 (62% identical), GPR27 (53% identical).
Diseases named in the same sentence as GPR173 in open-access papers:
GPR173 is named in the same sentence as 13 diseases in open-access papers, as found by Europe PMC text mining. Sharing a sentence is not in itself a finding about the gene and the disease. The quoted sentences say what the papers report.
endometriosis (5 papers, 2021 to 2025). The growth of functional endometrial tissue in anatomic sites outside the uterine body. "Women with endometriosis show reduced serum PNX levels as well as a reduced expression of GPR173 in the endometrium." (PMID 37815939, 2024). "The aim of the study was to determine PNX, FSH, LH, and 17β-estradiol association in women with endometriosis, and the expression of SMIM20/PNX signaling via GPR173." (PMID 34680544, 2021). "Interestingly, gonadotropin-releasing hormone analogs, used among others in the treatment of endometriosis, increase small integral membrane protein 20 gene expression and decrease GPR173 in the rats’ hypothalamus, pituitary, and ovaries." (PMID 39857742, 2025). "Moreover, some reproductive disorders are associated with altered levels of PNX/GPR173: the levels are higher in polycystic ovary syndrome (PCOS) while lower in endometriosis and cystic endometrial hyperplasia." (PMID 37815939, 2024). "Taken together, decreased THBS2 expression, accompanied by increased cell metabolism, might be one of the mechanisms through which endometriosis-specific concentration of PNX-14 in a GPR173-dependent manner modulates the viability and apoptosis of epithelial cells." (PMID 39857742, 2025). "In women with endometriosis, reduced PNX levels and GPR173 expression may be responsible for HPG axis dysregulation." (PMID 34680544, 2021). "Another hypothesis that may explain the decreased PNX expression in serum of women with endometriosis is that GPR173 is not the unique receptor for PNX binding." (PMID 34680544, 2021). "Women with endometriosis have significantly lower levels of serum PNX-14 and reduced expression of its receptor, GPR173, in ectopic ovarian lesions (lack of GPR173 protein within the ectopic glandular epithelium)." (PMID 39857742, 2025).
Anxiety (3 papers, 2020 to 2025). Intense feelings of nervousness, tension, or panic often arise in response to interpersonal stresses. "GPR173, also referred to as Superconserved Receptor Expressed in Brain 3 (SREB3), is primarily expressed in the brain and ovaries, aligning with PNX’s known functions in reproduction, anxiety regulation, and appetite stimulation." (PMID 39057043, 2024). "Again, a detailed investigation of the contribution of GPR173 to the pathophysiology of anxiety has not been reported yet." (PMID 32599826, 2020). "Of note, the high level of GPR173 expression in the brain (especially in the hypothalamus) appears to be well conserved from fish to mammals, which can be correlated with the central actions of PNX including GnRH and Kiss regulation and anxiolytic response for coping with anxiety." (PMID 40365230, 2025).
autoimmune disease (1 paper, 2024). A disorder resulting from loss of function or tissue destruction of an organ or multiple organs, arising from humoral or cellular immune responses of the individual to their own tissue constituents.
autoimmune pancreatitis (1 paper, 2022). "The antigens TOR1B and GPR173 had already been described as markers for discriminating PDAC from chronic and autoimmune pancreatitis." (PMID 35892825, 2022).
COVID-19 (1 paper, 2023). A disease caused by infection with severe acute respiratory syndrome coronavirus 2. "We developed a PRS model for severe COVID-19, which showed that variants detected in ZNF568, GPR173, PCDH15, and IGSF3 were associated with severe COVID-19." (PMID 37547597, 2023).
neuroblastoma (1 paper, 2017). Neuroblastoma (NB) is the most common solid, extracranial childhood tumor. "For MYCN, non-amplified stage 4 neuroblastoma, neurotrophic tyrosine kinase 1, or ALK paired with GFRA2, GFRA3, SSK1, GPR173, or with one another provided the most promising paired-hits." (PMID 28871274, 2017).
pyometra (1 paper, 2024). "Similarly, in canine cystic endometrial hyperplasia and pyometra, both PNX and GPR173 are downregulated." (PMID 37815939, 2024).
brain disorder (1 paper, 2023). A disease affecting the brain or part of the brain. "Thus, GPR173 might represent a promising therapeutic target for brain disorders related to excitation and inhibition imbalance in the cortex." (PMID 36813575, 2023). "We identified a novel CCK receptor, GPR173, localized in the CCK-GABA synapses and mediated the enhancement of the GABA inhibition effect, which might represent a promising therapeutic target for brain disorders related to excitation and inhibition imbalance in the cortex." (PMID 36813575, 2023).
GPR173 also shares sentences with these, for which no sentence is quoted: cancer (1 paper); Hypervolemia (1); laryngeal carcinoma (1); mental retardation (1); polycystic ovary syndrome (1).